IFNAR2 (interferon alpha and beta receptor subunit 2)
Diseases named in the same sentence as IFNAR2 in open-access papers (continued):
Sharing a sentence is not in itself a finding about the gene and the disease.
viral infection (continued). "The JAK proteins are phosphorylated upon binding of type I IFNs to IFN-α receptor 1 (IFNAR1) and IFNAR2, which then activate transcription factors such as STAT1 and STAT2 to induce transcription of ISGs that respond to viral infections." (PMID 40130878, 2025). "Ameliorating viral disease with dapsone or the downstream IFN-stimulated cascade with anti-IFNAR2 in the onset stages of disease must attenuate overactive immune-mediated respiratory inflammatory diseases." (PMID 36773052, 2023). "As the first line of antiviral defense, type I interferon (IFN) binds IFN receptor 1 (IFNAR1) and IFNAR2 to activate the Jak-STAT signal transduction pathway, producing IFN-stimulated genes (ISGs) to control viral infection." (PMID 33746965, 2021). "There was an elevated expression of IFNAR1 (IFNα/β receptor subunit 1), IFNAR2 (IFNα/β receptor subunit 2), IFNGR1 (IFNγ receptor subunit 1) and IFNGR2 (IFNγ receptor subunit 2) in MIS-C, bacterial infection and KD in comparison with viral infection." (PMID 39300098, 2024). "Importantly, the pK205R7PM mutant lost its ability to interact with IFNAR1 and IFNAR2, significantly weakening the inhibitory effect on IFN-I signaling both as a single protein and during viral infection." (PMID 39405340, 2024). "For example, G2/I2 showed hyper-editing of type 1 interferon (IFN) receptors (IFNAR1 and IFNAR2), type 1 IFN-stimulated genes (ISGs) (e.g., EIF2AK2, DDX58/RIG-1, MAVS, TRIM56, and TRIM69) and genes involved in immune responses to viral infection (EIF2AK2, DDX58/RIG-1, MAVS, CASP8, CYCS, and HMGB1)." (PMID 35406793, 2022). "A constitutive weak signal induced by IFN-β-IFNAR2 signalling allows epithelial cells to elicit a more robust response toward viral infection, while in the absence of this signal epithelial cells become hypo-responsive to this stimulus." (PMID 22396801, 2012). "As a control for specificity, we also found that virus infection does not alter the levels of IFNAR2 or the surface protein IGF1-β." (PMID 21998588, 2011). "This was further confirmed by adding exogenous IFN-α3 before virus infection, demonstrating that H1N1 infection was completely abrogated in wild-type cell lines while there was no change in H1N1 infected IFNAR2 KO cell lines." (PMID 28793350, 2017).
influenza (10 papers, 2012 to 2023). An acute viral infection of the respiratory tract, occurring in isolated cases, in epidemics, or in pandemics; it is caused by serologically different strains of viruses (influenzaviruses) designated A, B, and C, has a 3-day incubation period, and usually lasts for 3 to 10 days. "AR IRF9 deficiency, AR IRF7 deficiency, AD TLR3, and AR IFNAR2 deficiency also underlie influenza pneumonia." (PMID 36976641, 2023). "While cell surface receptor for type I IFNs consists of two distinct subunits (IFNAR1 and IFNAR2), almost all research on determining the role of type I IFNs in susceptibility to influenza and subsequent BSIs has focused solely on the involvement of IFNAR1 (using Ifnar1−/− mice)." (PMID 30473701, 2018). "Our findings suggest that IFNAR1- or IFNAR2-deficient patients may be prone to critical influenza." (PMID 36112363, 2022). "To further confirm the role of the constitutive IFN-β in influenza infection, we blocked the IFNAR2 during H3N2 infection with a neutralizing antibody." (PMID 22396801, 2012). "Increased levels of IFNAR2 at the cell surface could lead to a more responsive activation of the type I interferon pathway upon influenza infection, resulting in a greater antiviral response." (PMID 35739459, 2022). "It is intriguing that the known patients with AR IFNAR1 or IFNAR2 deficiency did not suffer from critical influenza." (PMID 36112363, 2022). "Our study revealed that IFNAR2 is required for effective anti-IAV immune responses, particularly as it relates to protection from influenza-mediated morbidity and mortality." (PMID 30473701, 2018).
pneumonia (10 papers, 2012 to 2024). An acute, acute and chronic, or chronic inflammation focally or diffusely affecting the lung parenchyma, caused by an infection in one or both of the lungs (by bacteria, viruses, fungi, or mycoplasma.). "Further indication of the importance of this pathway is the association between an IFNAR2 variant and susceptibility to pneumonia." (PMID 36167494, 2022). "Specifically, through a univariate regression analysis, we evaluated the association between risk allele carrier status for each genetic variant (OAS1/2/3, DPP9, IFNAR2, LZTFL1, ABO, and FUT2) and the development of clinical complications and of pneumonia." (PMID 36873632, 2023). "In an independent set of samples assayed using RT-qPCR, Ifnar2 and the interferon-responsive genes Cxcl11, Ifit1, Irf5 and Isg15 were confirmed to be upregulated during pneumonia." (PMID 28900269, 2017). "During pneumonia, lung neutrophils upregulated expression of Ifnar1 and Ifnar2 mRNA 2.3 and 1.5 fold, respectively (FDR < 0.05)." (PMID 28900269, 2017). "In hindsight, treatment of SARS-CoV2-induced pneumonia in P1 - even prior to a genetic diagnosis - likely facilitated relatively early recovery and survival given the well-known severity of SARS-CoV2 infection in IFNAR1/IFNAR2-deficient patients." (PMID 39098944, 2024). "Interestingly, in the interferon signaling pathways, Ifnar2 and the interferon-responsive genes Cxcl11, Ifit1, Irf5 and Isg15 were verified to be upregulated during pneumonia, documenting that neutrophils are well able to respond to type I interferon signaling." (PMID 28900269, 2017).
Down syndrome (7 papers, 2010 to 2026). "In contrast, over-expression of IFNAR1 and IFNAR2, as is the case in Down's Syndrome patients, where chromosome 21 is trisomic, results in an enhanced sensitivity to IFN." (PMID 21085662, 2010). "For example, four IFN receptor genes (IFNAR1, IFNAR2, IFNGR2, and IL10RB) and two IFN-stimulated genes (MX1 and MX2) are triplicated in Down syndrome, and individuals with Down syndrome exhibit hypersensitivity to type I IFN (IFN-I)." (PMID 38540156, 2024).
encephalitis (7 papers, 2017 to 2022). An acute inflammatory process affecting the brain parenchyma. "A patient with a polymorphism in IFNAR2 developed fatal encephalitis with the presence of RuV vaccine strain in a brain autopsy." (PMID 35631058, 2022). "By contrast, widespread dissemination of vRuV, including to the CNS, occurred within three weeks of MMR vaccination in a child with fatal encephalitis and IFNAR2 deficiency." (PMID 34107321, 2021). "In a case of homozygous IFNAR2 deficiency with fatal encephalitis after MMR, vMuV RNA was detected (alongside vaccine-strain rubella) in molecular analysis of brain tissue." (PMID 34107321, 2021). "Human IFNAR2 deficiency has also been linked to a fatal encephalitis with persistent measles IgM following vaccination with a measles-containing-virus." (PMID 31295941, 2019). "Mumps and rubella vaccine virus transcripts were detected in the brain of a child with IFNAR2 deficiency who developed fatal encephalitis following MMR vaccination, but brain immunohistochemistry was negative in this case (JB personal communication)." (PMID 27770235, 2017). "Currently, IFNAR2 SNVs have not been widely studied, but several of them have been investigated in the susceptibility to hepatitis B virus, and an utterly IFNAR2 deficiency was observed in cases of encephalitis-induced following measles, mumps, and rubella vaccination." (PMID 35967349, 2022).
glioma (7 papers, 2018 to 2025). A benign or malignant brain and spinal cord tumor that arises from glial cells (astrocytes, oligodendrocytes, ependymal cells). "This study established IFNAR2 as a prognostic risk factor in gliomas through integrative transcriptomic analyses." (PMID 41169364, 2025). "Collectively, this study innovatively proposes a mitophagy receptor-related risk signature as a prognostic stratification tool for gliomas, while identifying IFNAR2 as a novel therapeutic target." (PMID 41169364, 2025). "We present and validate a 17−MRRG prognostic model that links mitophagy receptors to glioma immunosuppression and clinical outcome, and identify IFNAR2 as a functional driver." (PMID 41169364, 2025). "Initial investigations demonstrated that IFNAR2 suppression markedly attenuated proliferative capacity, invasive potential, and migratory activity in both U87 and U251 glioma cell models." (PMID 41169364, 2025). "Transcriptomic analysis revealed significant upregulation of IFNAR2 mRNA in glioma tissues (P < 0.001), and the corresponding results were also reflected in 12 pairs of tumor tissues and peritumoral tissues from glioma patients." (PMID 41169364, 2025). "Given the unique biological role of IFNAR2, a critical component of the MRRG risk model in mitophagy and glioma progression, we have conducted comprehensive multi-omics investigations." (PMID 41169364, 2025). "GWAS genetic association analysis and experimental validation further elucidated the regulatory role of the key gene IFNAR2 in glioma progression." (PMID 41169364, 2025). "KM analyses across glioma cohorts demonstrated markedly reduced OS in IFNAR2-high patients (all, HR > 1, P < 0.001)." (PMID 41169364, 2025). "Functional in vitro and in vivo experiments demonstrated IFNAR2’s role in driving gliomas’ malignant progression via cell migration and invasion." (PMID 41169364, 2025). "Integrative analyses highlighted IFNAR2 as a central node; its silencing impaired glioma cell proliferation, invasion, and metastatic potential, while in vivo suppression attenuated tumor growth." (PMID 41169364, 2025). "We performed qRT-PCR analysis and found that the expressions of TNFAIP6, PSMB2, IRF4 and IFNAR2 were significantly upregulated in glioma tissues (n = 30) compared to normal brain tissues (n = 10)." (PMID 36712869, 2022). "We performed single-cell transcriptomic analysis on the orthotopic glioma mouse model (GSE246154) from the GEO database using R. The results indicated that the Ifnar2 gene was enriched in T cells, while the CD68 and CD33 genes were less enriched in macrophages." (PMID 40297576, 2025). "We then conducted a series of experiments to examine the role of IFNAR2 in glioma pathology." (PMID 41169364, 2025). "Furthermore, we uncovered IFNAR2 as a critical regulator driving glioma genesis." (PMID 41169364, 2025). "However, the silencing of IFN-α/β receptors 1 or 2 (IFNAR1 or IFNAR2), which constitute a loop to IFN-α signaling, causes a reduction in PD-L1 and MHC class I/II expression in glioma cells, as well as an enhanced susceptibility to immune cell lysis of NK cells." (PMID 29721184, 2018). "We detected IFNAR1 and IFNAR2 mRNA and protein and mRNA of ligands IFN-α and IFN-β in all human glioma cell lines tested." (PMID 36571986, 2023). "IFNAR2 and PARP9 show differences across all groups, while AFP and GFRA1 are significantly differentially expressed only between other gliomas and GBM." (PMID 36834486, 2023). "All five mouse glioma cell lines uniformly expressed mRNA for both type I IFN receptors, Ifnar1 and Ifnar2." (PMID 36571986, 2023). "CT-2A, GL-261, SMA-497, SMA-540 and SMA-560 murine glioma cells expressed IFN type I receptors IFNAR1 and IFNAR2 and were responsive to exogenous IFN stimulation." (PMID 36571986, 2023).
glioma (continued). "As the core subunit of type I IFN receptor, IFNAR2 orchestrates IFN signaling transduction and plays critical roles in tumorigenesis, necessitating comprehensive elucidation of its biological implications in glioma pathogenesis." (PMID 41169364, 2025).
HIV-1 infection (6 papers, 2012 to 2024). The type species of lentivirus and the etiologic agent of acquired immunodeficiency syndrome (AIDS). "To analyze the impact of HIV-1 infection on IFNα signaling, we determined the surface expression of IFNAR2 on NK cells, B cells, CD4+ and CD8+ T cells among LPMCs isolated from the gastrointestinal mucosa of 11 healthy donors, undergoing abdominal surgery." (PMID 31935222, 2020). "HIV-1 infection did not change the expression of either the surface bound or the soluble isoform of IFNAR2." (PMID 31935222, 2020). "Alterations in IFNAR expression in mucosal CD4+ T cells during HIV-1 infection may also contribute to our results, but our recent study have not detected significant changes in IFNAR2 expression in mucosal immune cells in PWH." (PMID 33064743, 2020).
lupus (6 papers, 2009 to 2023). "In the current study, we characterized the role of the IFNAR2 chain of the type I IFN (IFN-I) receptor in the targeting of nucleic acid-associated autoantigens and in B-cell expression of the nucleic acid-sensing Toll-like receptors (TLRs), TLR7 and TLR9, in the pristane model of lupus." (PMID 19624844, 2009).
ZIKV infection (6 papers, 2018 to 2024). "Consistent with our prior findings, a broad range of IFN, chemokine and cytokine genes were induced upon ZIKV infection in both IFNAR2-/- and isogenic IFNAR2+/+ iPS-Mφ, with IFNs predominating." (PMID 36439115, 2022). "This emphasised the profound alteration to the transcriptome of IFNAR2-/- iPS-Mφ at rest and upon ZIKV infection." (PMID 36439115, 2022).
diabetes (5 papers, 2016 to 2023). "When lacking the r type II interferon receptor (IFNAR2), diabetes happened only in female NOD mice." (PMID 33083497, 2020).
measles (5 papers, 2019 to 2022). A highly contagious viral infection caused by the measles virus. "At a molecular level IFNAR2 deficiency is reported to cause hemophagocytic lymphohistiocytosis (HLH) following measles-mumps-rubella vaccination because of excessive IFN signalling." (PMID 33637783, 2021). "Likewise, investigations including genetic variants in IFNAR2 are limited, but rare mutations in this gene have been found in patients with immunodeficiency after measles-mumps-rubella vaccination." (PMID 35967349, 2022).
melanoma (5 papers, 2016 to 2025). A malignant, usually aggressive tumor composed of atypical, neoplastic melanocytes. "The forest plot shows that IFNAR2, LBP, CXCL9, and TLR2 are the protective genes for melanoma, while RAC1 and MAPK10 are the risk genes for melanoma." (PMID 37666853, 2023). "Subsequently, employing a similar approach, we conducted a thorough analysis of the correlation between the clinical characteristics of melanoma and remaining five model genes, i.e. IFNAR2, LBP, MAPK10, RAC1, and TLR2." (PMID 37666853, 2023). "Both melanoma cell lines showed again a very comparable expression pattern of antiviral genes, with low expression of most genes, except for STING1, IFNAR1, IFNAR2, and IFIH1, which were moderately expressed." (PMID 40955425, 2025). "By integrating a series of bioinformatics methods, our study identified 6 TLR-related genes (IFNAR2, RAC1, LBP, TLR2, MAPK10, CXCL9), which have the potential to serve as new indicators of melanoma progression and prognosis." (PMID 37666853, 2023). "We further compared the expressions of IFNAR1 and IFNAR2 in normal skins, nevus tissues, and melanoma tissues using a published dataset (GSE3189) and found that the expressions of IFNAR1 and IFNAR2 are significantly higher in melanoma as compared to normal skin and nevus tissues." (PMID 35145233, 2022). "We found that the expression of IFNAR2, but not IFNAR1, is correlated with the enrichment of infiltrated CD8+ T cells in the metastatic melanoma tissue microenvironment." (PMID 35145233, 2022).
multiple sclerosis (5 papers, 2010 to 2022). A progressive autoimmune disorder affecting the central nervous system resulting in demyelination. "Two independent SNPs that tagged the multiple sclerosis (MS)-protective HLA class I alleles A*02/A*68 and B*44, respectively, were associated with increased levels of IFNAR2 in B and T cells, with the most prominent effect in IgD–CD27+ memory B cells." (PMID 33104735, 2020). "Moreover, the expression levels of both the receptor subunits IFNAR1 and IFNAR2 are associated with the INF-β treatment outcome in multiple sclerosis patients." (PMID 29713327, 2018). "Interferon beta-1b (Betaseron/Extavia) is a recombinant human interferon that binds to type I interferon receptors (IFNAR1 and IFNAR2) and is FDA-approved as an immunosuppressant to treat relapsing-remitting forms of multiple sclerosis." (PMID 35628390, 2022).
colorectal cancer (3 papers, 2022 to 2023). A primary or metastatic malignant neoplasm that affects the colon or rectum.
endometriosis (3 papers, 2022 to 2024). The growth of functional endometrial tissue in anatomic sites outside the uterine body. "This suggests that the IFNA/IFNAR2/JAK1 signaling pathway is essential in endometriosis progression." (PMID 39125716, 2024). "The mRNA levels of IFNα and its receptor 2 (IFNAR2) are elevated in the eutopic endometrium of endometriosis patients compared to healthy women." (PMID 39125716, 2024). "Notably, the transcription of IFNAR2 is significantly upregulated in the endometrium of women with endometriosis compared to their healthy counterparts." (PMID 39125716, 2024). "Therefore, an elevation of the IFN/IFNAR2/JAK axis is essential for endometriosis." (PMID 36358904, 2022). "The mRNA levels of IFNα and IFNAR2 are higher in the eutopic endometrium of endometriosis patients than in the endometrium of women without endometriosis." (PMID 36358904, 2022).
Sepsis (3 papers, 2016 to 2025). Sepsis is defined as life-threatening organ dysfunction caused by a dysregulated host response to infection. "Another possible interpretation is that IFNβ, in contrast to all other IFNα isoforms, have a unique non-Jak/STAT pathological signaling feature through IFNAR1, independent of IFNAR2 (the high affinity receptor for IFNα/β) as reported in a model of LPS-induced sepsis." (PMID 27792766, 2016).
autoimmune disease (2 papers, 2017 to 2019). A disorder resulting from loss of function or tissue destruction of an organ or multiple organs, arising from humoral or cellular immune responses of the individual to their own tissue constituents. "IFNAR2 is one of the type I interferon receptors, which are currently considered as key factors in the development and regulation of autoimmune diseases such as RA." (PMID 31366403, 2019).
chronic hepatitis C (2 papers, 2012 to 2023). "Chronic hepatitis C patients’ carriers of the rs2229207 C allele (IFNAR2) and combined treatment with pegylated-interferon-alpha (PEG IFN-alpha) and ribavirin showed an association (p = 0.02) with the increased risk (OR, 2.07) of presenting a sustained virological response (SVR)." (PMID 38003785, 2023). "They found the IFNAR2 expression level in the liver is predictive of the response to IFN-α treatment in chronic hepatitis C patients." (PMID 22863531, 2012). "rs2834158, rs3153, and rs2236757 (IFNAR2) have not been significantly statistically associated with treatment response in chronic hepatitis C patients." (PMID 38003785, 2023).
cytomegalovirus infection (2 papers, 2021 to 2022). A herpesvirus infection caused by Cytomegalovirus. "Intriguingly, progressive hemophagocytosis after MMR vaccine or cytomegalovirus infections was noted in two of the previously reported cases, as well as in patients with other defects in the type I IFN pathway including STAT1, STAT2, and IFNAR2." (PMID 35091979, 2022).
epilepsy (2 papers, 2015 to 2020). A brain disorder characterized by episodes of abnormally increased neuronal discharge resulting in transient episodes of sensory or motor neurological dysfunction, or psychic dysfunction. "Within the network, many genes are related to inflammation and apoptosis, such as MAPK1, ATM, MYD88, RBL1, TRAF6, PIK3CD, IFNAR2, etc, indicating that these miRNAs may play a role in drug-resistant epilepsy through inflammation and apoptosis." (PMID 25984652, 2015).